DHRS7B (dehydrogenase/reductase 7B)
Description:
Reductase required for adipogenesis and activation of PPARG nuclear receptor. Can convert acyl and alkyl dihydroxyacetone-phosphate (DHAP) into glycerolipids and ether lipids, respectively, synthesizing ether-linked phospholipids that act as agonists for PPARG. Also regulates adipogenesis by preventing adipocyte browning: following import into the nucleus, interacts with PRDM16, inhibiting the interaction between PRDM16 and PPARG and preventing differentiation of brown adipocytes.
Synonyms: PexRAP; SDR32C1; CGI-93; DKFZp566O084; MGC8916
Tractability: Antibody: UniProt predicts a signal peptide or a membrane-spanning region; the Human Protein Atlas places it where antibodies can reach. PROTAC: ubiquitination databases record sites on it; its protein half-life has been measured.
Gene: Protein-coding gene on chromosome 17 (21,123,364 to 21,193,265, forward strand). Ensembl gene ENSG00000109016.
Subcellular location: Peroxisome membrane; Endoplasmic reticulum membrane; Nucleus
Subcellular location (Human Protein Atlas): Cell Junctions; Cytosol; Plasma membrane
Pathways (Reactome):
Metabolism: Plasmalogen biosynthesis
Gene Ontology:
Molecular function: acylglycerone-phosphate reductase (NADP+) activity; oxidoreductase activity, acting on the CH-OH group of donors, NAD or NADP as acceptor
Biological process: ether lipid biosynthetic process
Cellular component: membrane; endoplasmic reticulum membrane; nucleus; peroxisomal membrane; bounding membrane of organelle; cytoplasm
Genetic constraint (gnomAD): Loss-of-function variants: 24 observed, 28.63 expected, observed/expected ratio (o/e) 0.84, 90% interval 0.61 to 1.18. The upper end of that interval is the gene's LOEUF score, 1.18, which puts it in group 5 of 6, group 1 being the genes least tolerant of losing a copy. Missense variants: 368 observed, 438.75 expected, observed/expected ratio (o/e) 0.84, 90% interval 0.77 to 0.91. Synonymous variants: 142 observed, 174.22 expected, observed/expected ratio (o/e) 0.82, 90% interval 0.71 to 0.94.
Homologues: Orthologues: chimpanzee DHRS7B (99% identical), macaque DHRS7B (95% identical), dog DHRS7B (86% identical), rabbit DHRS7B (82% identical), guinea pig DHRS7B (81% identical), pig DHRS7B (78% identical), rat Dhrs7b (77% identical), mouse Dhrs7b (76% identical), tropical clawed frog dhrs7b (66% identical), zebrafish dhrs7b (55% identical), Drosophila melanogaster CG7601 (44% identical), Caenorhabditis elegans dhs-30 (36% identical), and 10 more. Paralogues in human: DHRS7C (41% identical), DHRS7 (26% identical), RDH8 (22% identical), HSD11B1 (20% identical), DHRS2 (20% identical), HSD11B1L (19% identical), DHRS11 (19% identical), DHRS4 (19% identical), HSDL2 (17% identical), CBR1 (16% identical), CBR3 (16% identical), DHRS4L2 (15% identical), and 1 more.
Diseases named in the same sentence as DHRS7B in open-access papers:
DHRS7B is named in the same sentence as 8 diseases in open-access papers, as found by Europe PMC text mining. Sharing a sentence is not in itself a finding about the gene and the disease. The quoted sentences say what the papers report.
delirium (1 paper, 2025). A disorder characterized by confusion; inattentiveness; disorientation; illusions; hallucinations; agitation; and in some instances autonomic nervous system overactivity. "There were eight protective genes (DHODH,DHRS7B,TOP1MT,CASP8,GFM1,CPT1B,TK2,GPD2), and four genes (SCP2,DMPK,GSTK1,SIRT3) that increased delirium risk, as shown inFigure 2, withp = 0.05 (dotted line); and false discovery rate (FDR) < 0.05 (red asterisks)." (PMID 41330563, 2025). "Our findings show that higher expression of 8 genes, includingDHODH,DHRS7B,TOP1MT,CASP8,GFM1,CPT1B,TK2, andGPD2, could decrease the risk of delirium." (PMID 41330563, 2025).
DHRS7B also shares sentences with these, for which no sentence is quoted: cancer (1 paper); endothelial dysfunction (1); Hypertension (1); ischemia (1); monocytopenia (1); neutropenia (1); Obesity (1).